CTNNB1 (catenin beta 1)
Diseases named in the same sentence as CTNNB1 in open-access papers (continued):
Sharing a sentence is not in itself a finding about the gene and the disease.
tumor (continued). "Since we had very small group of tumours with CTNNB1 mutations, we could not study the effects of alternative activation of Wnt pathway and its potential influence on EMT." (PMID 36969079, 2023). "Furthermore, being a driver event, all tumor cells are expected to harbor a CTNNB1 variant, regardless of tumor heterogeneity." (PMID 38201440, 2023). "However, other members of the WNT signaling pathway like the tumor suppressor genes APC, Axin1, or Axin2/Conductin were shown to harbor mutations as alternative genetic alterations, while only CTNNB1 and APC mutations were found in a substantial fraction of WNT-MBs." (PMID 36181537, 2022). "Consequently, our analysis of tumor immune infiltrating cells within the TME of THCA tumor revealed that the high expression levels of the DPP4/CTNNB1/MET signature correlate positively with the infiltration levels of tumor-associated macrophages, regulatory T cell, and cancer-associated fibroblast." (PMID 35205190, 2022). "Desmoid tumor cell lines lacking detectable CTNNB1 mutation could primarily be composed of fibroblasts cells and not tumor cells as a possible explanation for the lack of BC2059 effects on DT wild type cell lines." (PMID 36240209, 2022). "While other studies have reported a failure to detect CTNNB1 mutations in a proportion of ACP samples, these results rather reflect methodological limitations such as an insensitive sequencing approach and/or a low proportion of the analyzed tumor tissue in the samples that were analyzed." (PMID 35954494, 2022). "However, in HCC with CTNNB1 gene mutations, the recruitment of pro-inflammatory dendritic cells and, therefore, T cells to the tumor is abrogated by suppressing the production of chemokines CCL4 or CCL5 by tumor cells." (PMID 34632251, 2021). "Moreover, the risk of relapse in tumours with CTNNB1 exon 3 mutation is independent of other clinicopathological prognostic factors, such as FIGO stage, tumour grade, DNA MMR-deficient protein expression, or presence of LVSI." (PMID 34420090, 2021). "In contrast to this, pathways which promote tumor growth and drug resistance (such as Wnt target, obesity acid elongation, drug metabolism by cytochrome P450 and fatty acid biosynthesis), showed significantly more activity in the CTNNB1-MUT group than in the CTNNB1-WT group (all P < 0.05)." (PMID 34777372, 2021). "In a sporadic WT1 mutation case the first mutation occurs in a specific kidney cell, likely followed by a CTNNB1 mutation in the same cell, but this cell might not form a tumor." (PMID 33379206, 2020).
tumor (continued). "Tumour subtype-specific sex-biased driver mutations included CTNNB1 mutation frequency in liver hepatocellular cancer (Liver-HCC), with more male-derived samples harbouring CTNNB1 mutations: (male: 31%, female: 13%, 95% CI: 8.1–28%, prop-test q = 0.048, LGR q = 1.4 × 10−3)." (PMID 32859912, 2020). "The tumor is categorized as wild-type (WT) in case no CTNNB1 exon 3 mutations are found." (PMID 33194643, 2020). "PPI analysis indicated that the levels of the mRNAs encoding RBPJ, SKP1, CTNNB1, CDH2, SCG2, VGF, and TFF3 were significantly increased in PanNEN tumor tissues compared with the matched paratumor tissues and may be involved in the DNER signaling pathway in PanNENs." (PMID 33329729, 2020). "Cells with a heterozygous WT1 mutation (first hit) that also harbor a CTNNB1 mutation could not be identified in our cell culture conditions but they may exist in the tumor in vivo." (PMID 33379206, 2020). "Furthermore, previous report of pilomatrical CS investigating both β-catenin expression and CTNNB1 gene exon 3 mutation showed aberrant β-catenin expression in the tumor without mutation, which is consistent with our case." (PMID 32005258, 2020). "Furthermore, when intravenous delivery of CTNNA1 and CTNNB1 siRNAs loaded with CA nanoparticles was done in the 4T1 tumor bearing the Balb/c mice model, the reduced tumor volume compared to the CA nanoparticle treated controls indicated the role of these genes in tumorigenesis." (PMID 31269666, 2019). "Interestingly, in one tumor with the presence of ALK protein expression, neither mutation in exon 3 of the CTNNB1 gene nor nuclear β-catenin immunoreactivity were detected, but the tumor was classified to the WNT group by application of NanoString method." (PMID 30523493, 2019). "However, in our case, we found novel mutations in CTNNB1 and VEGFR-2 genes that may be related to TBSCC and overexpression of VEGF and VEGFR-2 genes were observed in the tumor tissue." (PMID 28915721, 2017). "Our results support the hypothesis that somatic mutations in CDH1 or CTNNB1 are not a major contributor to cancer cell detachment, and thus play a limited role in the etiology of tumor metastasis." (PMID 29156750, 2017). "In one of these HCC, 3 different subclonal mutations of CTNNB1 (cancer cell fraction = 5, 30, and 39%) affected the D32 and S33 hotspots suggesting that the WNT/ß-catenin pathway activation was selected independently in several clones late during tumor progression in this patient." (PMID 29101368, 2017). "In conclusion, we present evidence that TERT promoter and CTNNB1 mutations have a high frequency in HCC of viral origin, particularly in HCV-related HCC, and are very specific to the tumor tissues given their constant absence in the autologous non-tumor cirrhotic tissues." (PMID 27276713, 2016). "However, in HCC patients, serum LECT2 levels were not significantly different in tumor with CTNNB1 or without CTNNB1 mutations when compared to patients with chronic liver disease or healthy volunteers." (PMID 24892551, 2014). "No other mutations or LOH were found in the two CTNNB1 mutated tumours." (PMID 21901162, 2011). "Therefore, none of the samples displaying CTNNB1 nuclear staining were sequenced and no IHC result was obtained for any of the tumours containing mutations." (PMID 19293793, 2009).
tumor (continued). "Thus, taking also the DNA sequencing results into account the S37A mutation was homozygous in these 4 tumours, rather than hemizygous with one mutant and one deleted CTNNB1 allele." (PMID 18541010, 2008). "The heterogeneity in the prevalence of CTNNB1 mutations may also reflect the complex cellular composition of the tumor, which includes distinct neoplastic and non-neoplastic subpopulations such as senescent cells, tumor germ cells, and cells with different cytokeratin (CK) expression profiles." (PMID 40433410, 2025). "In mechanism, we found that MIDN interacted with the CTNNB1/MMP9 axis, which was verified as an important pathway in suppressing the tumour immune microenvironment." (PMID 40111059, 2025). "While most tumor meta-programs exhibited melanocytic differentiation (high MITF and CTNNB1), two meta-programs-Respiration and Stress-expressed dedifferentiation markers including AXL, SOX9, EGFR and NGFR." (PMID 40890106, 2025). "Clinical characteristics of patients and tumours categorised according to LEF-1 (median 48.0) and CTNNB1 RNA expression (median 49.5) based on Nanostring nCounter." (PMID 40130164, 2025). "MEF2A transcriptionally upregulates the expression levels of catenin beta 1 (CTNNB1) and zinc finger E-box binding homeobox 2 (ZEB2) in CRC to promote tumor progression." (PMID 40592832, 2025). "CircMVP mediated CTNNB1 m6A modification by promoting METTL3 activation and inhibited B7-H3-dependent anti-tumor immune response in CRC." (PMID 39744434, 2025). "Our Protein–protein interaction (PPI) network analysis results demonstrated that the key target genes of FSH for anti-tumor treatment were AKT1, EGFR, BCL2, CTNNB1 and HSP90AA1." (PMID 40230723, 2025). "The mRNA expression analysis revealed that THBS2, CTNNB1, COL4A1, and E2F3 were significantly upregulated in tumor tissues compared to normal gastric tissues in the TCGA-STAD cohort." (PMID 41291892, 2025). "In PC, the genes ESR1 and SRC exhibited overexpression in tumor tissues, whereas IL1B and CTNNB1 showed reduced expression." (PMID 41186627, 2025). "Upregulation of miR-142-3p suppressed growth of CRC cells and xenograft tumor by downregulating CD133, ABCG2, and Lgr5, CDK4, and CTNNB1." (PMID 40868120, 2025). "In BC, the genes STAT3, CTNNB1, and MYC were upregulated, while TNF was downregulated in tumor tissues." (PMID 41186627, 2025). "WNT pathway mutations have been identified in nearly all PC cases, with alterations in genes such as CTNNB1 and RNF43 contributing to tumor initiation and progression." (PMID 40869017, 2025). "As expected, CTNNB1 expression is present in all groups; canonical WNT signaling via β-catenin is active in healthy individuals and is also activated in tumor cells in MM." (PMID 40650009, 2025). "Promoter methylation analysis using the UALCAN database revealed that THBS2, CTNNB1, COL4A1, and E2F3 exhibited significantly lower promoter methylation levels in STAD tumor tissues compared to normal controls." (PMID 41291892, 2025). "Here, we showed that the lack of LIN28A and LIN28B had no impact on liver development or function, but largely abrogated tumor initiation driven by powerful oncogenes such as NRAS, CTNNB1, YAP, and AKT." (PMID 38875287, 2024). "The mRNA expression of six inflammation-related genes (C3, CTNNB1, CYBC1, DNASE1L3, IRAK1, and SERPINE1) is closely related to the overall survival rate, tumor immune infiltration, and clinical stage of HCC patients." (PMID 39055701, 2024).
tumor (continued). "Thus, overall, we observed that β-catenin inhibition alone for CTNNB1-mutated HCC is most effective in early-stage disease setting as evident through significant tumor responses in multiple models of CTNNB1-mutated HCC, and as partial responses in β-catenin non-mutated HCC models." (PMID 39711542, 2024). "It was supposed that the cytotoxic activity was due to the reduction in the expression of CTNNB1 and LRP6 genes, which in turn reduces cell proliferation and delays tumor expansion." (PMID 39478959, 2024). "The HE staining revealed that our collected pT3-TRIM71 samples all had HCC-like characteristics and were distinctly different from classic HB (YAP5SA + CTNNB1) and ICC (YAP5SA + AKT) tumor tissues." (PMID 39267787, 2024). "H&E- and HA-stained liver sections confirmed tumor formation and HA-tagged MYC and CTNNB1 expression in tumors." (PMID 39353892, 2024). "In turn, CD8 Tex cells in the LN-out highly expressed TGF-β1, IFN-γ, and ITGB1, which target FN1, EGFR, CTNNB1, COL1A1, and CFLAR in tumor cells, activating downstream pathways including ERK1 and ERK2 cascade." (PMID 38519500, 2024). "Based on our data, CD8 Tex cells in LN-out upregulate of TGF-β1, IFN-γ, and ITG-β1, which subsequently target FN1, EGFR, CTNNB1, and COL1A1 in tumor cells, activating the ERK1 and ERK2 cascade pathways and facilitating tumor progression." (PMID 38519500, 2024). "To further validate these findings, we conducted qPCR analysis to assess the expression of ESR1, BRCA1, CTNNB1, and BAX in tumor tissue." (PMID 39045563, 2024). "Our pilot study investigated mRNA expression of the SWI/SNF chromatin-remodelling complex gene ARID1A, NOTCH receptors, WNT pathway genes CTNNB1 and FBXW7 mRNA expression in two OC cell cultures as well as 51 gynaecologic tumour tissues." (PMID 36982928, 2023). "Our computer-based analysis revealed that the messenger (m)RNA levels of VEGFA, CTNNB1, MMP7, and CD44 oncogenic signatures were upregulated in tumor samples compared to normal samples of patients with CRC tissues, with significant p values (<0.05)." (PMID 36672201, 2023). "HE staining and immunohistochemistry staining for Ki67, CTNNB1, and LEF1 was performed to measure their expression levels in tumor tissues." (PMID 37740194, 2023). "In a cohort of 38 samples from 20 patients, QUENCH’s effectiveness in detecting CTNNB1 ctDNA was assessed and compared with ddPCR ctDNA and AFP levels, evaluating correlations with tumor burden and treatment response." (PMID 38201440, 2023). "In vivo xenograft tumor models were established in nude mice using MDA-MB-231 cells simultaneously stably overexpressing LYPLAL1-DT and β-catenin (termed LYPLAL1-DT + CTNNB1), as well as Vector cells or LYPLAL1-DT cells." (PMID 38111678, 2023). "Here we report that selective ablation of stearoyl CoA desaturase-2 (Scd2) in aHSC globally suppresses nuclear CTNNB1 and YAP1 in tumors and tumor microenvironment and prevents liver tumorigenesis in male mice." (PMID 37156770, 2023). "Results showed that the high value of regulatory potential between MFAP5 and some of its top predicted NOTCH1/WNT pathway target genes (CCND1, HES1, MYC, RBPJ, NOTCH1, CCN3, CTNNB1 and SOX17) in inferring signaling paths in tumour tissues." (PMID 36855786, 2023). "We compared the expression level of six frequently used markers for WNT activation (CTNNB1/beta-catenin, TCF1, TCF4, FZD7, MYC and CCND1) in normal and tumor tissue." (PMID 37149691, 2023).
tumor (continued). "Our pilot study investigated the expression of ARID1A and the NOTCH receptors and WNT components CTNNB1 and FBXW7 in two OC cell cultures, then validated the results in gynaecologic tumour tissues." (PMID 36982928, 2023). "The organoids’ morphology was found similar to that of the primary tumor, and organoids expressed typical CP markers, including cytokeratin 7 (CK7), CD133 and catenin beta 1 (CTNNB1)." (PMID 37614709, 2023). "Genetic or pharmacological inhibition of LTB4R2 recapitulates CTNNB1 and YAP1 inactivation and tumor suppression in culture and in vivo." (PMID 37156770, 2023). "The CTNNB1 (coding gene of β-catenin) KD CRC cells displayed upregulated FAO-related genes, whereas the WT tumor cells exhibited enhanced glycolytic capacity." (PMID 37063423, 2023). "Using the Kruskal–Walls test to compare data, we found that overexpression of VEGFA, CTNNB1, MMP7, and CD44 genes promoted primary tumor and cancer metastasis in CRC tissues." (PMID 36672201, 2023). "The results of WNTs’ mRNA level assessment in the MSCs of the tumor niche in MM suggest possible prospects for mRNAs of WNT2B, WNT9B and CTNNB1 as being molecular prognostic markers that can predict the outcome of the disease." (PMID 37239457, 2023). "EMT genes like KRT19, CTNNB1 and TWIST1 and the hypoxia marker HIF1A were significantly changed in tumors, indicating altered tumor microenvironment." (PMID 37170215, 2023). "The identified potential tumor suppressor genes included DAG1, SLC39A8, TMEM173/STING1, RDX, TJP1, CTNNB1, and SMC3." (PMID 36499305, 2022). "Except for one tumor specimen (subject 43), APC and CTNNB1 genetic aberrations were mutually exclusive." (PMID 34986841, 2022). "Proliferative tumours were characterized by high expression of the c-MET, ARID1A, CTNNB1, RAF1, LGR5, and GLUL1 genes." (PMID 36345011, 2022). "Since we did not perform corresponding tumor genome sequencing in our cohort, it is difficult to reach definite conclusions, but our ctDNA profiling results suggest that a CTNNB1 mutation might not have a large impact on the efficacy of combination immunotherapy in HCC patients." (PMID 35884434, 2022). "β-catenin, as a product of the oncogene CTNNB1, has been reported to be involved in WNT signalling and plays a significant role in tumour cell EMT and cancer metastasis." (PMID 35637955, 2022). "The expression of classical CTNNB1‐dependent transcriptional Wnt targets such as AXIN2 and NKD1 was elevated in a large fraction of tumor samples compared with normal tissue." (PMID 35904277, 2022). "We found that AXIN1, CTNNB1 and LEF1 were highly expressed in tumor tissues and FZD4 was highly expressed in normal tissues in TCGA cohort." (PMID 36703749, 2022). "We first investigated the upregulated four genes (BDNF, PTGS2, CTNNB1, and GSK3B) in the tumor sample expression profile in CC patient tissue using RNAseq data." (PMID 35054980, 2022). "Similar increase was also observed in some of the key Wnt pathway genes such as CTNNB1, AXIN1 and AXIN2 suggesting a peak of immune exclusion in S2 tumours." (PMID 35301339, 2022). "Then, we picked out 8 HAIRGs (VEGFA, CTNNB1, PPARG, HSP90AA1, HMOX1, LGALS3, SPP1, and RAC1) from the 17 HAIRG model through the LASSO Cox regression, upregulated genes accounted for 7/8 in tumor tissue, which was shown by a heat map." (PMID 35069936, 2022). "We further analyzed the role of DPP4, CTNNB1, and MET expressions in promoting THCA progression and tumor metastasis." (PMID 35205190, 2022).